EGFR (epidermal growth factor receptor)
Diseases named in the same sentence as EGFR in open-access papers (continued):
Sharing a sentence is not in itself a finding about the gene and the disease.
tumor (continued). "Given our findings that QSOX1-S suppresses integrin/FAK and EGFR/Raf/ERK pathways, we propose that QSOX1-S may in part also suppress tumor invasion and metastasis, and promote apoptosis of HCC cells through an inhibition of the integrin/FAK and EGFR/Raf/ERK pathways." (PMID 30962950, 2019). "Atezolizumab, nivolumab, and durvalumab indications are independent of PD-L1 expression, while pembrolizumab is restricted to patients whose tumours do not have EGFR or ALK genomic aberrations and express PD-L1 with a tumour proportion score (TPS) ≥1% determined by an FDA-approved test." (PMID 31262041, 2019). "The tumor of the palate mucosa was likewise identified as an adenocarcinoma, and the cells showed cytological similarities with the tumor cells in the pleural effusion; TTF-1, Napsin A, EGFR mutation and ALK translocation were all negative." (PMID 30634950, 2019). "Comparing with Anti-IL-2 and EGFR inhibitor, a combination of castration with Anti-WNT5A or PLX yields better anti-tumor responses, indicating that blockade of the PC-Treg or PC-TAM interaction may effectively reduce tumor cell growth." (PMID 31504033, 2019). "Moreover, gene detection in exosomes showed great consistency, no matter compared with tumor tissues, cell blocks or both of them, indicating perfect performance of exosome as a tumor DNA source for EGFR detection." (PMID 31608233, 2019). "Second, there is no consideration of tumor location; this is because the efficacy of anti-EGFR monoclonal antibody in right-sided colon cancer was first reported in ASCO 2016 while the protocol of the present study was waiting approval from the ethics committee." (PMID 31238905, 2019). "After 2 years of follow-up, the pooled results from both cohorts showed that continued clinical benefit was observed with nivolumab plus ipilimumab in all patients, including those patients with tumor PD-L1 expression ≥1% and ≥50%, regardless of EGFR status, smoking status, or histology." (PMID 31871778, 2019). "Here, tumor cells showed increased EGFR expression levels compared to their wildtype counterparts, despite the fact that none of the tested organoids showed any evidence for EGFR amplification." (PMID 31694307, 2019). "Interestingly, functional studies showed that USP8 can enhance tumor initiation and progression of lung carcinoma, likely stabilizing receptor tyrosine kinases (RTK), such as EGFR or p-MET, through the interaction with stratifin (SF), a recently identified oncogene." (PMID 31487906, 2019). "As such, the evaluation of EGFR expression in the primary tumor may not be suitable for predicting the treatment response of metastases." (PMID 30736475, 2019). "Thus, the understanding of biological traits involved in drug sensitivity, such as sensitivity to EGFR-inhibitors, could be further elucidated by combining DSRT with molecular profiling of the individual tumor." (PMID 31889236, 2019). "The use of PDT after EGFR-CPIG and anti-PD-L1 antibodies IV administration in a CRC murine model demonstrated a synergistic action of these two therapies combined, causing complete tumor eradication with no relapses over time." (PMID 31662751, 2019). "EGFR signaling triggers intracellular signaling pathways such as the STAT signaling pathway, phosphoinositide 3-kinase (PI3K)/Akt pathway, and the Ras/Raf/MEK/ERK1/2 pathway, which enhances tumor cell proliferation, angiogenesis, invasion, metastasis, and apoptosis resistance." (PMID 31759360, 2019). "Since the activation of mTOR has been shown to contribute to tumour progression, it can be speculated that the honokiol-induced inhibition of cell proliferation in HNSCC cells is mediated through the downregulation of EGFR/mTOR signalling pathway." (PMID 31877856, 2019).
tumor (continued). "RTKs, such as VEGF receptor, EGFR, fibroblast growth factor receptor, platelet-derived growth factor receptor, RET and KIT, are responsible for several biological signaling pathways involved in the regulation of angiogenesis, oncogenesis and the tumor microenvironment." (PMID 31856912, 2019). "However, EGFR-targeting mAb fragments do not bind to murine EGFR, limiting proper evaluation of the real tumor-to-background signal of these agents in preclinical models." (PMID 30213849, 2019). "IHC detection of EGFR expression in bulk tumor tissue alone, for example, may not be an ideal tool for prediction of response to gefitinib." (PMID 31635038, 2019). "Unfortunately, and despite the fact that we used adjacent tumor sections, we are currently not able to judge whether GLI1 positive tumor cells are completely devoid of EGFR expression." (PMID 31867038, 2019). "Exogenous transfected miR-27a led to a decreased level of EGFR and inhibition of miR-27a led to EGFR increased in cSCC cells, indicating that miR-27a suppressed the expression of EGFR by binding to 3′UTR region, which is consistent with the tumor suppressive role of miR-27a in cSCC." (PMID 32039029, 2019). "Furthermore, in spite of EGFR inhibition, overexpression of SCD1 in vivo significantly promoted tumor growth by activating EGFR/PI3K/AKT signaling in tumor tissues, but A939572 treatment restricted SCD1-induced tumor progression and inhibited EMT phenotype of cancer cells in vivo." (PMID 31019378, 2019). "Furthermore, EGFR and CCND1 CNAs have an additive effect on OSCC tumor progression." (PMID 31159251, 2019). "Based on data from the recent phase 3 trial, the PD-1 inhibitor pembrolizumab was approved by the U.S. Food and Drug Administration (FDA) for the first-line treatment of metastatic NSCLC whose tumors have 50 percent or more PD-L1 expression with no EGFR or ALK genomic tumor aberration." (PMID 30679441, 2019). "In our study, we found that some EGFR-TKI mechanisms may upregulate PD-L1 expression and promote the immune escape ability of EGFR-TKIs resistant NSCLC tumours, but it does not indicate an absolute response to anti-PD-1/PD-L1 therapies." (PMID 31747941, 2019). "Because HGF may increase EGFR-TKI resistance, PD-L1 expression, and immune escape in NSCLC, we explored the regulatory mechanisms of PD-L1 expression in HGF-mediated EGFR-TKI resistant NSCLC tumours." (PMID 31747941, 2019). "Moreover, HER2-positive CTCs were detectable despite the HER2 negative primary tumor and growth factor receptors (EGFR, IGFR, and FGFR) were expressed in CTCs." (PMID 31261643, 2019). "Of 3081 eligible patients enrolled in 6 trials involving anti-EGFR agents, 2684 patients (87.1%) could be analyzed after excluding those without any tumor-size information or with tumor-size measurements available only more than 24 months after randomization." (PMID 31539075, 2019). "Interestingly, membranous staining for EGFR was observed in more than 95% of the tumor cells of the patient tumor, whereas staining was absent in all the cells of subcutaneous PDX and PDOX." (PMID 31732509, 2019). "CXCR7 may interact with EGFR and promote MAPK signaling and tumor cell progression." (PMID 30935067, 2019). "Recently, a computational model was developed, linking cell surface receptor (EGFR) activation, the MAPK signalling pathway and tumour growth to determine whether ERK inhibitor drugs may be of benefit for CRC patients with the frequently occurring BRAFV600E mutation." (PMID 31430887, 2019).
tumor (continued). "Among general resistance mechanisms, chronic/intermittent hypoxia and hypoxia-inducible factors are known to adversely impact tumor response to radiation and chemotherapy in many types of cancer, and especially in HNSCC where hypoxia and HIF-1 have been shown to induce the upregulation of EGFR." (PMID 31640284, 2019). "Several pathways have been discovered to be involved in SCD1-regulated tumor characteristics, such as the AMP-activated protein kinase (AMPK) pathway, the phosphatidylinositol-3 phosphate kinase (PI3K)/Akt/mTOR pathway, and the epidermal growth factor receptor (EGFR) pathway." (PMID 31019378, 2019). "Anti-EGFR therapies consequently have been in the focus of attention: antibodies, tyrosine kinase inhibitors (TKIs), or vaccines were tested in GBM patients, but largely remained unsuccessful, due to limited drug delivery to the brain, tumor heterogeneity, and acquired resistance." (PMID 32642659, 2019). "For instance, a clinical study has shown that patients with MET-amplified esophagogastric cancer (EGC) develop resistance after about two months of MET inhibitor therapy, mainly due to the rapid growth of non-MET (EGFR or HER-2) amplified tumor cell subpopulations." (PMID 30849971, 2019). "The fact that, differently from what we observed for anti-EGFR antibodies, the efficacy of Bevacizumab was not influenced by primary tumor location, may possibly indicate a predictive effect of primary tumor location." (PMID 31762802, 2019). "Notably, trastuzumab and cetuximab could efficiently stimulate the ADCC activity of canine NK cells even against tumor cells, which weakly express HER-2 and/or EGFR." (PMID 31610784, 2019). "In vivo, the inhibition of tumor growth coincided with a significant decrease in proliferation, and a reduction in the expression of growth factors known to drive malignant tumor progression phenotypes including angiogenesis such as VEGF and hyperproliferation such as, PDGF, FGF, EGFR, and HGRF." (PMID 31192543, 2019). "Furthermore, we could examine the proportion of specific biomarker-expressing tumor cells in each PDC, such as HER-2, EGFR, and MET etc. before anti-cancer drug-sensitivity test." (PMID 31850215, 2019). "In our study, EGFR-positive expression was significantly correlated with tumor invasion depth and regional lymph node metastasis (P < 0.05) but not with the age, gender, tumor diameter and pathology grading (P > 0.05)." (PMID 33817143, 2019). "This discrepancy could be attributed to tumour heterogeneity since the FFPE block contained both EGFR-positive and negative areas." (PMID 31747973, 2019). "Consequently, RNAi-suppression of the tumor EGFR has an anti-angiogenic effect within the tumor that is not observed in the normal brain." (PMID 31998120, 2019). "Previous studies have identified several predictive biomarkers, including the expression of PD-L1 on tumor cells, for PD-1/PD-L1 blockade therapies in NSCLC patients; however, the usefulness of these biomarkers in NSCLCs with EGFR mutations has not been elucidated." (PMID 30978241, 2019). "EGFR was expressed on >99% of cells for all tumor cell lines (data not shown)." (PMID 31903167, 2019). "A third limitation is the absence of tumor characteristics, i.e., EGFR expression." (PMID 31013858, 2019). "Integration of these two signaling pathways converges in the regulation of HH/EGFR response genes, such as SOX2, SOX9, JUN, CXCR4, and FGF19, which are cooperatively induced in response to HH and EGFR signaling activation in BCC and in tumor-initiating pancreatic cells." (PMID 31244888, 2019).
tumor (continued). "As NRP1 is a promiscuous coreceptor for different growth factor receptors, its depletion or inactivation may inhibit various signaling cascades starting from VEGFR2, EGFR, and MET, and thus, may aid to curb cell proliferation and tumor angiogenesis and oncogene addiction." (PMID 30717262, 2019). "In addition, the focal high gain of the MYC locus (chr8) with at least 6 copies was identified in clones C and F and amplification of EGFR (chr7) was identified at over 35 copies in the bulk tumour samples but none of the derived clonal samples." (PMID 30736342, 2019). "Its overexpression in the non-anti-EGFR eligible G12V tumor might have been an important implication for chemotherapy." (PMID 31805664, 2019). "After engraftment of the tumor cells, freshly isolated and non-stimulated PBMCs from a healthy donor were injected i.v., followed by a saline control, the paired EGFR, and Her2/neu specific hemibodies or an EGFR-specific BiTE control, which were administered s.c.." (PMID 31772172, 2019). "However, it is difficult to extrapolate these results to the in vivo setting since EGFR might respond not only to EGF but also to TGF-α, AR, EPGN, BTC, HB-EGF and EREG, which are also increased in tumor tissues." (PMID 31921216, 2019). "In this study, RYNXC could significantly decrease ESR1, PGR, EGFR, PTGS2, and Src mRNA expressions in a dose-dependent manner in MCF-10AT cells or breast precancerous lesion model rats, which could further inhibit cell proliferation and tumor progression." (PMID 30906412, 2019). "In our study, we identified only two NSCLC patients with ALK-rearrangements among those with EGFR/KRAS wild-type tumours, so we could not use these data in statistical analyses." (PMID 30953094, 2019). "In SUM159 and SCP2 human tumor cells, as model cells for triple-negative breast cancer, CBD effectively inhibited epidermal growth factor (EGF)-induced tumorigenic properties of these cancer cells by obstructing signaling pathways for EGFR, Akt, ERK, and NF-κB." (PMID 30987191, 2019). "In August 2018, FDA has approved an expanded label for pembrolizumab in combination with pemetrexed and platinum chemotherapy for the first-line treatment of patients with metastatic nonsquamous NSCLC, with no EGFR or ALK genomic tumor aberrations, based on results of the KEYNOTE-189 trial." (PMID 31205619, 2019). "We found that the difference in the sensitivity to the same type of tumor cell may be correlated with the EGFR expression level, but this is not the only crucial factor." (PMID 30372581, 2019). "Inhibition of EGF/EGFR signaling by the widely utilized anti-tumor drug gefitinib greatly inhibited TGIF2WT-promoted metastasis of H1299 xenografts as monitored in vivo by the luciferase assay, which was further confirmed by counting the tumor burden shown by HE staining." (PMID 31871777, 2019). "Analysis of the quantification of these results demonstrates a significant increase in nuclear pNFkB expression in ESCC tumor samples that had both down-regulated p120ctn and overexpressed EGFR, when compared to control tumor samples (defined as tumors without both genes modified)." (PMID 29541406, 2018). "Both findings suggest that there could be, additionally to the inter-tumor variability, a high intra-tumor heterogeneity additively influencing the outcome of anti-EGFR treatments in a negative way." (PMID 29848954, 2018). "We demonstrated that the AF1280 antibody could successfully detect EGFR on the plasma membrane of HPV38 tumour sections but not in TC-1 derived tumours." (PMID 29552307, 2018). "These two different schedules were designed to evaluate EGFR’s effects in a highly injurious/inflammatory state (schedule 1) or a healed state (schedule 2), potentially allowing differential assessment of EGFR’s tumor-altering functions in the presence or absence of injury." (PMID 29904166, 2018).
tumor (continued). "Mice containing both the CCSP-rtTA and EGFRL858R genes, but not either singly, express the EGFR mutant only when fed doxycycline-containing food and subsequently develop lung hyperplasia (as seen in the micro-CT images) and discrete tumor nodules (as shown in the histology images)." (PMID 30590030, 2018). "Our data showed that there was a higher proportion of CD3+CD8+ EGFR-CAR T cells (54.91%) compared with UTD cells (34.88%), indicating that the cytotoxic T lymphocyte (CTL) population increased significantly after co-culture of these EGFR-CAR T cells with tumor cells." (PMID 29415996, 2018). "However, for patients who had sensitizing EGFR mutations and had been treated by EGFR-TKI, we did not observe any survival benefit conferred by main tumor resection." (PMID 29435191, 2018). "In general, tumor tissue obtained by surgery or biopsy has been used for EGFR genotyping in patients with NSCLC, among whom 27–31% of biopsies may fail to acquire tumor tissue that is suitable for EGFR genotyping at diagnosis or during disease progression." (PMID 30526536, 2018). "Here, we demonstrated that tumour cell proliferation in three different human cancer cell lines (A549, SW837, MCF7) had the potency to be activated by a synchronised and synergetic activation of EGFR or via electrical dipole interactions between tiny size RE-NPs and the LABS of integrins on a cell." (PMID 30465280, 2018). "While we have focused on mutations in EGFR, resistance alterations in other genes, such as MET amplification, could render a tumor non-responsive to any EGFR targeted therapy." (PMID 30481207, 2018). "For example, the decision of whether a patient should receive anti-EGFR therapy for CRLM cannot solely be based on the expression of EGFR in the primary tumour if the expression levels are not corresponding to those in multiple metastases." (PMID 30602942, 2018). "Also the original study describing the prognostic value of EGFR levels used the I-125-EGF binding assay in membrane preparations of frozen biopsies without controlling the tumor to stroma ratio." (PMID 29989001, 2018). "An assessment of anti-EGFR affibody molecules ZEGFR:2377 labeled with gallium-68 via the commonly used DOTA (1,4,7,10-Tetraazacyclododecane-1,4,7,10-tetraacetic acid); chelator showed a high liver uptake (6.2 ± 0.3% ID/g) and relatively low tumor uptake (2.7 ± 0.1% ID/g) 3 h after injection." (PMID 30231504, 2018). "In addition, the percentages of EGFR-positive tumor cells were not different between DFSP-T and DFSP peripheral areas (p > 0.20)." (PMID 29492209, 2018). "Case 1 exhibited high expression of EGFR in tumor tissue after showing no response to alectinib." (PMID 29844868, 2018). "Seven days later, tumor cells could no longer be detected in the treatment group receiving the bivalent α-EGFR-EGFR TM." (PMID 29876011, 2018). "Moreover, in vivo administration of 7A7 in an EGFR-expressing HPV38 tumour model did not have any impact on tumour regression or animal survival." (PMID 29552307, 2018). "Hence, we concluded that KRAS WT status was not sufficient to select patients who can achieve tumor response to anti-EGFR therapies." (PMID 29352306, 2018). "Interestingly, the combination of treatments induced a prolonged transcriptional activation of nuclear EGFR gene signature compared to individual stimuli (from 2-4 to 8h), indicating that the PGE2 and EGF cooperate in their activities to sustain tumor progression." (PMID 29599917, 2018). "We confirmed that EGFR protein is only being measured in the tumor, as immunohistochemistry using an EGFR antibody cross-reactive to mouse and human in both untreated and ErbB3-antibody-treated tumors showed that only the HNSCC tumor cells and not the stroma express EGFR." (PMID 29305574, 2018).